CXCL1 (C-X-C motif chemokine ligand 1)
Diseases named in the same sentence as CXCL1 in open-access papers (continued):
Sharing a sentence is not in itself a finding about the gene and the disease.
breast carcinoma (continued). "In addition, we detected the mRNA levels of CXCL1-3 and CXCL8 in cancer tissues, and CXCR2 and LIF in adipocytes adjacent to breast cancer of clinical breast cancer specimens." (PMID 35280694, 2022). "Colon cancer samples from the TCGA showed high expression of CXCL1, 3, 5, 6, and 11 and low expression of CXCL12 (fold change > 2); the Bittner poly-cancerous dataset confirmed the differential expression of CXCs in colon cancer and breast cancer." (PMID 34439306, 2021). "Next, we investigated whether suppressing TAM/CXCL1-induced Treg differentiation and infiltration is the central mechanism of ADQ in inhibiting breast cancer immune escape and metastasis." (PMID 34461944, 2021). "Similarly, TCGA data analysis revealed elevated expression patterns of CXCL8, CXCL1, and CXCL5 in ER- breast cancer specimens." (PMID 33912188, 2021). "Taken together, our study demonstrated that XIAOPI formula could prevent breast cancer PMN formation and lung metastasis via inhibiting TAMs/CXCL1 signaling." (PMID 32213179, 2020). "Interestingly, CXCL1 and CXCL2, including those produced by TAMs, were identified as capable of contributing to metastasis and chemoresistance in a mouse spontaneous breast cancer model." (PMID 33238581, 2020). "CXCL1 has been found to positively correlate with colon cancer progression, and poor prognosis in breast cancer; PAI-1 also plays an important role in tumor progression, invasion, and metastasis in breast cancer." (PMID 33256011, 2020). "Moreover, ID4 enhances the angiogenic potential of breast cancer cells through the post-transcriptional regulation of IL8, CXCL1, and VEGFA mRNAs and through the reprogramming of tumor-associated macrophages." (PMID 32054109, 2020). "Additionally, high levels of CXCL1, CXCL3, CXCL5, CXCL6, CXCL7 and CXCL8 are observed in drug-resistant breast cancer cells, which diminishes the effectiveness of other medical interventions." (PMID 31788042, 2019). "Meanwhile, CXCL1 administration could abrogate the inhibitory effect of XPS on breast CSCs subpopulations and mammospheres formation abilities in the co-cultured breast cancer cells." (PMID 31803057, 2019). "CXCL1 administration could significantly increase the ALDH+ subpopulations and mammospheres numbers in breast cancer cells." (PMID 31803057, 2019). "In addition, CXCL1, a cognate ligand of CXCR2, has also been reported to promote metastasis of breast cancer via CXCR2." (PMID 31390756, 2019). "More importantly, XPS significantly inhibited mammary tumor growth, breast CSCs subpopulation, and TAMs/CXCL1 activity in mouse 4T1-Luc xenografts in vivo without any detectable side effects." (PMID 31803057, 2019). "Similarly, CXCL1 and CXCL2 secretion by breast cancer cells resulted in increased infiltration of pro-tumorigenic myeloid cells and was further augmented by chemotherapeutic treatment, leading to chemoresistence." (PMID 30319622, 2018). "A breast cancer tissue microarray further validated that CXCL1 was more expressed in breast cancer tissue compared with normal adjacent tissue." (PMID 30158589, 2018). "Although, co-expression of Plac1 and Cxcl1 in breast cancer tissue has not been reported, Cxcl1 expression in breast cancer biopsies was found to be elevated in metastases, and inversely related to ERα expression and relapse-free survival." (PMID 29632317, 2018). "Here in, cytokine array validated that C-X-C motif chemokine ligand 1 (CXCL1) is the most abundant chemokine secreted by TAMs, and CXCL1 can promote breast cancer migration and invasion ability, as well as epithelial–mesenchymal transition in both mouse and human breast cancer cells." (PMID 30158589, 2018).
breast carcinoma (continued). "Cxcl1 modulates MDSC infiltration in prostate tumors and rhabdomyosarcomas, is a prognostic marker of poor outcome in breast cancer and promotes metastasis in an MDA-MB-231 breast cancer xenograft model." (PMID 29487713, 2018). "We also identified CXCL1 as the most secreted cytokine from TAMs, and CXCL1 reduction using neutralizing antibody or shRNA in TAMs blocked breast cancer cell metastasis in vitro and in vivo, suggesting a role for TAM-secreted CXCL1 in mediating metastasis and its potential as a therapeutic target." (PMID 30158589, 2018). "However, CXCL1 knockdown in THP-1 cells not only blocked the growth-promoting effects of macrophages, but also significantly reduced breast cancer growth compared with control mice." (PMID 30158589, 2018). "Interestingly, CXCL-1 and CXCL-10 were unaltered in breast cancers whereas significant increased levels were detected in dense breast tissue." (PMID 29387062, 2017). "Surprisingly, no significant upregulation of the extracellular CXCL-1 was detected in breast cancers whereas dense breast tissue exhibited at least three times higher levels than non-dense breast tissue." (PMID 29387062, 2017). "IL-1β indirectly induces motility in cancer cells through mesenchymal stem cells (MSC)-dependent release of chemokines such as CXCL1, 2, 3, 5, 6, 8, CCL2, 3, 5, and 20 suggesting correlation between interaction of these cells and the metastatic potential of the breast cancer cells." (PMID 28609459, 2017). "CXCL1/GRO-α mediates lung metastasis and chemoresistance in breast cancer." (PMID 26379707, 2015). "CXCL1 is overexpressed in ERα negative breast cancers and high CXCL1 levels are correlated with reduced relapse-free survival and metastasis." (PMID 26618099, 2015). "We observed that decreased TGFBR2 expression in human breast cancer patients correlated with decreased CXCL1, but not with CXCL5 in HER2+, PR + and ER + tumors." (PMID 25280532, 2014). "4–5 weeks post-tumor cell implantation, thioglycollate elicited macrophages from DA-3 scramble shRNA control or DA-3 SEMA7A shRNA mammary tumor-bearing mice were analyzed for the production of pro-angiogenic chemokines CXCL2/MIP-2, CXCL1 and matrix metalloprotease MMP-9." (PMID 24550834, 2014). "Furthermore, peritoneal elicited macrophages from mice bearing SEMA7A-silenced tumors produce significantly (p < 0.01) lower levels of angiogenic proteins, such as CXCL2/MIP-2, CXCL1, and MMP-9, compared to those from control DA-3 mammary tumors." (PMID 24550834, 2014). "The lung metastasis signature presented by Minn and coworkers has been developed using a CXCL1 and -2 positive cell line, yet in human breast cancers, CXCL1 and -2 are not expressed at considerable levels, and in only a small minority of cases." (PMID 20030852, 2009). "Finally, transcriptomic analysis of large datasets of cancer cell lines of different lineages, including breast cancer provided additional evidence of a lack of correlation between neutrophil guidance cues (CXCL8 and CXCL1) and EMT-associated genes." (PMID 40833805, 2025). "Taken together, our study implicates CXCL1 as a critical role in ERBC growth and metastasis via crosstalk with fibroblast and cotargeting CXCR1/2 and CDK4/6 could potentially overcome endocrine resistant breast cancer." (PMID 38393465, 2024). "Breast cancer cells, including triple negative breast cancer, upon pharmacological IRE1 inhibition, display reduced expression of immune modulators such as interleukin 8 (IL-8), C-X-C Motif Chemokine Ligand 1 (CXCL1), or transforming growth factor-beta 2 (TGF2)." (PMID 37721642, 2023). "Notably, CUMS did not increase CXCL1 levels in the non-tumor-bearing mice, suggesting that the elevated CXCL1 was primarily derived from breast cancer tissue." (PMID 37210553, 2023). "Another source of CXCL1 in breast tumors may be adipose-derived mesenchymal stem cells (MSC), which increase CXCL1 expression under the influence of interleukin-1β (IL-1β) from breast cancer cells." (PMID 37108425, 2023).
breast carcinoma (continued). "After quantitative calculation, the levels of serum CCL18 and CXCL1 antigens, and C1D, TM4SF1, FXR1, and ZNF573 IgG autoantibodies were significantly higher in patients with OC than in those with cervical cancer, liver cancer, breast cancer, gynecological benign tumor patients, and healthy women." (PMID 34995016, 2022). "At present, there are no studies determining plasma CXCL1 levels in patients with breast cancer." (PMID 36431173, 2022). "Finally, in vivo studies were conducted to investigate whether ADQ inhibited breast cancer immune escape and lung metastasis by suppressing the TAM/CXCL1/Treg pathway." (PMID 34461944, 2021). "For example, CXCL1 derived from TAMs could recruit hematopoietic stem and progenitor cells (HSPCs) and induce their differentiation into MDSCs to shape the immunosuppressive TME and favor breast cancer metastasis." (PMID 34461944, 2021). "For example, current studies have discovered that dormant breast cancers could promote MSC to release exosomes including distinct miRNA such as miR-127, -197, -222, and -223, driving breast cancer cells into quiescence through reducing the expression of CXCL1." (PMID 34712663, 2021). "Given that MEKi elicit immunologic effects as well as direct antitumor effects and are actively being combined with immune checkpoint inhibitors in breast cancer, suppression of MDSC recruitment via transcriptional inhibition of CXCL1/2/8 may be a novel mechanism of combinatorial activity." (PMID 32634121, 2020). "While others have shown that CXCL1 is highly expressed within breast tumor and stromal cells, including immune cells and carcinoma-associated fibroblasts (CAF), the critical upstream pathways have not been clearly delineated in breast cancer." (PMID 33256011, 2020). "Similarly, the exogenous CXCL1 could partly restore MMP2 and MMP9 levels that were suppressed by XIAOPI formula, suggesting that XIAOPI might inhibit the invasion of breast cancer cells in a CXCL1 dependent manner." (PMID 32213179, 2020). "Our data showed overexpression of proinflammatory factors including CXCL1, CXCL2, CXCR4, CCL3, CCL4, IL-8, and PTGS2/COX-2 in the peripheral blood of patients with breast cancer both when considering the subtypes individually and when considering all breast cancer samples as a group." (PMID 26884644, 2016). "However, the prognostic significance of CXCL1 expression in breast cancer has not been fully characterized." (PMID 25344051, 2014). "This hypothesis is supported by previous studies on CXCL1 expression in the MMTV-PyVmT transgenic mouse model, where CXCL1 functioned to recruit myeloid immune suppressor cells that enhanced survival and invasion of mammary tumors." (PMID 25344051, 2014). "This indicates that CXCL1 may not play an important role in all cases of breast cancer." (PMID 37108425, 2023). "However, it should be noted that breast cancer cells produce CXCL1, but it is not known whether CXCL1 concentrations are high enough to exceed the detection threshold when determined by a given analytical method from peripheral blood samples." (PMID 36431173, 2022). "Considering that TAM/CXCL1 activity within the TME represents a reliable target for TCM to prevent breast cancer immune escape and metastasis, it is important to analyze whether ADQ also suppresses breast cancer metastasis by remodeling the immunosuppressive TME via modulating TAM/CXCL1 activity." (PMID 34461944, 2021). "Another study showed that expression in breast cancer decreases with increasing tumor grade, while another showed that CXCL1 expression does not differ between grade I and III breast cancers." (PMID 37108425, 2023). "CXCL1 expression in CAF is increased under the influence of basal-like breast cancer cells, while luminal breast cancer cells do not increase CXCL1 expression in CAF." (PMID 37108425, 2023).
breast carcinoma (continued). "After being co-cultured with AD-MSCs, the secretome of the breast cancer cell line MCF7, but not MDA-MB-231, was found to be more angiogenic; this was mediated by CXCL1 and CXCL8 released by AD-MSCs." (PMID 31130595, 2019). "Flow cytometry data showed that CXCL1 treatment did not increase CD44+/CD24- or aldehyde dehydrogenase assays (ALDH+) in the MDA-MB-231 and MCF-7 breast cancer cell lines, indicating that CSC-enhancing effects may not explain CXCL1-induced metastasis." (PMID 30158589, 2018).
melanoma (121 papers, 2007 to 2025). A malignant, usually aggressive tumor composed of atypical, neoplastic melanocytes. "HSP90/phosphorylated IKK-rich extracellular vesicles from hypoxic melanoma activate pro-angiogenic melanoma-associated fibroblasts (MAFs) via the NF-κB/CXCL1 axis." (PMID 39148727, 2024). "Individuals having a duplicated region on chromosome 4q13 have an increased predisposition to developing various cancers, including melanoma; this is the locus of the CXCL1 gene and other CXCR2 ligands." (PMID 38673949, 2024). "Human melanoma cells release CXCL1, which has mitogenic characteristics and is linked to melanoma aetiology." (PMID 35958781, 2022). "CXCL1, a chemokine originally identified in melanoma, is associated with oncogenesis, tumor progression, and metastasis across several tumor entities by recruiting tumor-associated neutrophils." (PMID 33572437, 2021). "Up-regulated expression of IL-8 and CXCL1 were also associated with NF-kB transcription factor activity in cultured melanoma cells." (PMID 28129639, 2017). "CXCL1 was originally reported as a secreted cytokine by human melanoma cells and implicated in melanoma pathogenesis." (PMID 26618099, 2015). "PARP-1 binding of the NF-κB immediate upstream region (IUR) element activates transcription of CXCL1, which encodes melanoma growth stimulatory activity protein and is overexpressed in the progression of malignant melanoma." (PMID 24350055, 2013). "Our melanoma invasion signature is associated with upregulation of critical NF-κB effectors including CXCL1, FMN2, MMP1, IL-8, IGFBP3 which have been implicated in the regulation of tumor cell proliferation, motility, migration, and/or invasion." (PMID 17611626, 2007). "In particular, TNF-α, produced by tumour-associated macrophages (TAMs), modulates the overexpression of CXCL1 involved in cancer development and malignant progression; CXCL1 overexpression is associated with an aggressive form of melanoma, as it promotes tumour growth and metastasis." (PMID 37627054, 2023). "The increase in CCL2, IL8, and CXCL1 was already observed in melanoma-associated fibroblasts." (PMID 35538545, 2022). "Similarly, Cox2-dependent PGE2 can modulate the secretome of BrafV600E-expressing melanoma cells; loss of Cox2 was associated with reduced Il6 and Cxcl1, among other factors, consistent with our findings." (PMID 33730589, 2021). "We further delineate that expression of osteopontin, IL-6 and the melanoma derived chemokine C-X-C motif ligand 1 (CXCL1) in the bone marrow increases after high fat diet, predisposing melanoma cells to home into the bone likely due to enhanced osteoclast activation." (PMID 27049717, 2016). "We were particularly interested in the NF-κB pathway as a mediator of melanoma invasion since our most highly upregulated invasion-specific genes, CXCL-1 and IL-8, have previously been reported to be activated by NF-κB and had previously been implicated in melanoma progression." (PMID 17611626, 2007). "The high expression of CXCL1 in malignant melanoma may be due to mutations." (PMID 38673949, 2024). "STRING-based PPI networks centered on TGF-β revealed high-confidence connectivity with fibrotic, angiogenic, and immunomodulatory cytokines such as VEGF, Galectin-3, and CXCL1, which the Dox-treated melanoma cells also enriched in their released EVs." (PMID 40943445, 2025). "CXCL1 from malignant melanoma cells also acts on keratinocytes together with bFGF, CXCL8/IL-8, and VEGF-A." (PMID 38673949, 2024). "Five genes (CXCL10, TNF, PIK3CD, PIK3R2, and CXCL1) of the TNF signalling pathway and seven genes (CXCL9, GDF15, BMP7, TNFRSF15, CXCL10, TNF, and CXCL1) of the cytokine–cytokine receptor pathway were commonly upregulated in melanoma cells." (PMID 39496484, 2024). "Once CXCL1 is secreted, it activates its receptor CXCR2, which further increases CXCL1 expression in malignant melanoma cells, as well as induces tumor cell proliferation." (PMID 38673949, 2024).